ENSG00000253049
Gene: Small nucleolar RNA gene on chromosome 3 (3,102,913 to 3,103,015, forward strand). Ensembl gene ENSG00000253049.
Homologues: Paralogues in human: SNORA17B (78% identical), SNORA17A (48% identical).